DUSP7 (dual specificity phosphatase 7)
Description:
Dual specificity protein phosphatase. Shows high activity towards MAPK1/ERK2. Also has lower activity towards MAPK14 and MAPK8. In arrested oocytes, plays a role in meiotic resumption (By similarity). Promotes nuclear envelope breakdown and activation of the CDK1/Cyclin-B complex in oocytes, probably by dephosphorylating and inactivating the conventional protein kinase C (cPKC) isozyme PRKCB (By similarity). May also inactivate PRKCA and/or PRKCG (By similarity). Also important in oocytes for normal chromosome alignment on the metaphase plate and progression to anaphase, where it might regulate activity of the spindle-assembly checkpoint (SAC) complex (By similarity).
Synonyms: PYST2; MKP-X; MKPX
Tractability: PROTAC: ubiquitination databases record sites on it.
Gene: Protein-coding gene on chromosome 3 (52,048,919 to 52,056,571, reverse strand). Ensembl gene ENSG00000164086.
Subcellular location: Cytoplasm
Pathways (Reactome):
Signal Transduction: ERKs are inactivated; Negative regulation of MAPK pathway; RAF-independent MAPK1/3 activation
Disease: Signaling by MAPK mutants
Gene Ontology:
Molecular function: MAP kinase tyrosine/serine/threonine phosphatase activity; protein binding; protein serine/threonine phosphatase activity; protein tyrosine phosphatase activity; MAP kinase tyrosine phosphatase activity; protein tyrosine/serine/threonine phosphatase activity; protein tyrosine/threonine phosphatase activity
Biological process: negative regulation of MAP kinase activity; peptidyl-tyrosine dephosphorylation; ERK1 and ERK2 cascade; MAPK cascade; negative regulation of ERK1 and ERK2 cascade; negative regulation of MAPK cascade
Cellular component: cytoplasm; cytosol; nucleoplasm
Genetic constraint (gnomAD): Loss-of-function variants: 7 observed, 24.03 expected, observed/expected ratio (o/e) 0.29, 90% interval 0.17 to 0.55. The upper end of that interval is the gene's LOEUF score, 0.55, which puts it in group 2 of 6, group 1 being the genes least tolerant of losing a copy. Missense variants: 400 observed, 514.8 expected, observed/expected ratio (o/e) 0.78, 90% interval 0.71 to 0.84. Synonymous variants: 287 observed, 246.71 expected, observed/expected ratio (o/e) 1.16, 90% interval 1.06 to 1.28.
Homologues: Orthologues: chimpanzee DUSP7 (99% identical), macaque DUSP7 (99% identical), mouse Dusp7 (99% identical), guinea pig DUSP7 (98% identical), pig DUSP7 (98% identical), rat Dusp7 (98% identical), zebrafish dusp7 (76% identical), tropical clawed frog dusp7 (69% identical). Paralogues in human: DUSP6 (64% identical), DUSP9 (51% identical), DUSP1 (27% identical), DUSP2 (26% identical), DUSP4 (26% identical), DUSP16 (26% identical), DUSP8 (26% identical), DUSP10 (25% identical), DUSP5 (25% identical), SSH1 (25% identical), SSH2 (25% identical), SSH3 (22% identical), and 19 more.
Diseases named in the same sentence as DUSP7 in open-access papers:
DUSP7 is named in the same sentence as 25 diseases in open-access papers, as found by Europe PMC text mining. Sharing a sentence is not in itself a finding about the gene and the disease. The quoted sentences say what the papers report.
breast carcinoma (14 papers, 2007 to 2026). "Loss of DUSP7 promotes oestrogen‐dependent growth of breast cancer cells, and increased DUSP7 expression levels have been associated with reduced proliferation and invasion of renal cancer cells." (PMID 37962020, 2023). "Consistently, silencing of circABCB10 restored paclitaxel sensitivity by inducing apoptosis and inhibiting invasion and autophagy in chemoresistant breast cancer cells through the let-7a-5a/dual specificity phosphatase 7 (DUSP7) axis." (PMID 33050642, 2020). "LncRNA MIAT promoted breast cancer progression by regulating miR-155-5p to regulate DUSP7 expression in breast cancer, and promoted proliferation and invasion of hepatocellular carcinoma cells via regulating miR-214." (PMID 29487526, 2018). "Clinical data analysis reveal that DUSP7 expression is lower in ER+ breast cancer samples than that in ER- breast cancer." (PMID 29041978, 2017). "To determine the clinical relevance of DUSP7 in breast cancer, we interrogated the TCGA breast cancer database at Oncomine and found that DUSP7 was lower in ER+ breast cancer samples (n = 225) than in ER- samples (n = 87)." (PMID 29041978, 2017). "Our results suggested that MIAT acted as a competing endogenous RNA (ceRNA) to regulate the expression of dual specificity phosphatase 7 (DUSP7) by taking up miR-155-5p in breast cancer." (PMID 29100300, 2017). "The results suggested that MIAT functions as oncogene partly through influencing DUSP7 expression in breast cancer through miR-155-5p." (PMID 29100300, 2017). "Taken together, these results suggest that linc-RoR promotes estrogen-independent growth and activation of MAPK/ERK pathway of breast cancer cells by regulating the ERK-specific phosphatase DUSP7." (PMID 29041978, 2017). "Our results indicted that DUSP7 was a direct target of miR-155-5p and its expression was higher in basal like breast cancer than other subtypes." (PMID 29100300, 2017). "We conclude that MIAT promotes breast cancer progression and functions as ceRNA to regulate DUSP7 expression by sponging miR-155-5p in breast cancer." (PMID 29100300, 2017). "For instance, it was reported that upregulated hsa_circ_0006528 contributed adriamycin-resistant in breast cancer via the miR-1236-3p/CHD4 axis and circABCB10 was overexpressed in breast cancer that was involved in paclitaxel resistance through the circRNA/let-7a-5p/DUSP7 axis." (PMID 34980129, 2022). "To further extend this finding, we investigated that MIAT acted as a ceRNA to regulate DUSP7 mRNA by taking up miR-155-5p in breast cancer cells, which might be one of the mechanisms of MIAT functions as an oncogene." (PMID 29100300, 2017). "There were positive correlation between MIAT and DUSP7 expression in breast cancer patients." (PMID 29100300, 2017). "We proposed that MIAT acted as a ceRNA to regulate DUSP7 mRNA by taking up miR-155-5p in breast cancer cells, which might be one of the mechanisms of MIAT as an oncogene." (PMID 29100300, 2017). "And we also found DUSP7 expression was higher in basal-like breast cancer (P<0.05)." (PMID 29100300, 2017). "There were positive correlation between MIAT and DUSP7 in breast cancer patients (R=0.226, P<0.05)." (PMID 29100300, 2017). "Together, these results highlight the clinical significance of DUSP7 in breast cancer." (PMID 29041978, 2017). "Finally, the clinical data analysis also supports the significance of DUSP7 in breast cancer." (PMID 29041978, 2017). "To understand the mechanism of MIAT regulation in breast cancer, we indicated that MIAT shared miR-155-5p response element with DUSP7, which belongs to DUSP family." (PMID 29100300, 2017). "In addition, FOSL1 also mediates the dephosphorylation of proliferation and apoptosis bridging protein 15 (PEA15) by upregulating dual-specificity phosphatase 7 (DUSP7), which increases drug resistance in breast cancer." (PMID 36061185, 2022).
breast carcinoma (continued). "Moreover, ROR activated the MAPK/ERK pathway and upregulated the expression of dual specificity phosphatase 7 (DUSP7), an ERK-specific phosphatase, thereby facilitating estrogen-independent proliferation of breast cancer cells." (PMID 34527584, 2021). "The expression of MIAT and DUSP7 were all negative or all positive in the consecutive sections of breast cancer TMA." (PMID 29100300, 2017). "There were positive correlation between DUSP7 expression and MIAT in breast cancer patients." (PMID 29100300, 2017).
cervical cancer (2 papers, 2021 to 2024). A primary or metastatic malignant neoplasm involving the cervix. "Previous studies have shown that PDL1 promotes cervical cancer development by activating RAS pathway, while DUSP7 prevents cervical cancer progression by inactivating RAS pathway." (PMID 38152044, 2024). "DUSP7 is decreased in cervical cancer tissues compared with normal tissues." (PMID 34435746, 2021). "DUSP7 inhibits cervical cancer progression by inactivating the RAS pathway." (PMID 34435746, 2021). "In this analysis, high expression of DUSP7 significantly inhibited the proliferation, invasion and migration ability and EMT process of SIHA cervical cancer cells." (PMID 34435746, 2021). "The expression level of PLD1 is not affected by the upregulation or downregulation of DUSP7, and the effect of PLD1 on the progression of cervical cancer is not dependent on the activity status of DUSP7." (PMID 34435746, 2021).
Sepsis (2 papers, 2019 to 2023). Sepsis is defined as life-threatening organ dysfunction caused by a dysregulated host response to infection. "Overexpressed miR-107 causes TNF-α secretion through regulating dual-specificity phosphatase 7(DUSP7) in circulating endothelial cells, which may lead to tubular cell damage in sepsis-induced AKI." (PMID 31658856, 2019).
alopecia (1 paper, 2022). Hair loss usually from the scalp. "DUSP4 (dual specificity phosphatase 4) and DUSP7 (dual specificity phosphatase 7) were upregulated in giant pandas with alopecia." (PMID 35413801, 2022).
autoimmune disease (1 paper, 2019). A disorder resulting from loss of function or tissue destruction of an organ or multiple organs, arising from humoral or cellular immune responses of the individual to their own tissue constituents. "Besides DUSP22 downregulation in SLE patients, other DUSPs (DUSP2, DUSP7, DUSP10, and DUSP12) are also downregulated or mutated in human autoimmune diseases." (PMID 31766293, 2019). "DUSP2, DUSP4, DUSP7, DUSP10, DUSP12, DUSP22, and DUSP23 are involved in human autoimmune diseases, including SLE." (PMID 31766293, 2019). "In addition, DUSPs are also involved in either human autoimmune diseases (DUSP2, DUSP7, DUSP10, and DUSP12) or T-cell activation (DUSP1, DUSP5, and DUSP14)." (PMID 31766293, 2019).
breast tumors (1 paper, 2017). "For instance, DUSP7 level is lower in ER+ breast tumors than in ER- breast tumors." (PMID 29041978, 2017).
kidney cancer (1 paper, 2017). Primary or metastatic malignant neoplasm involving the kidney. "Despite a report that high expression of DUSP7 may play a role in development of leukemia, other studies also suggest that a low level of DUSP7 is associated with progression of kidney cancer." (PMID 29041978, 2017).
systemic lupus erythematosus (1 paper, 2023). An autoimmune multi-organ disease typically associated with vasculopathy and autoantibody production. "KEGG analysis showed that the molecules upregulated in patients with high DUSP7 levels were mainly enriched in transcriptional misregulation in cancer, systemic lupus erythematosus, salivary secretion, renin-angiotensin system, and relaxin signaling pathway." (PMID 37538139, 2023).
cancer (11 papers, 2012 to 2025). A tumor composed of atypical neoplastic, often pleomorphic cells that invade other tissues. "Nevertheless, considering the paucity of studies focused on the role of DUSP7 in cancer, further studies are needed to further characterize its role in cancer." (PMID 40943262, 2025). "DUSP7, whose full name is dual specificity phosphatase 7, has been reported involved in various pathophysiological processes, especially in cancers." (PMID 37538139, 2023). "Although DUSP7 was studied in cancer cell lines and even sparked interest as a potential cancer drug target, it remains one of the less studied DUSPs." (PMID 36227898, 2022). "Some reports suggested that DUSP7 exhibited reduced expression in particular cancers as tumour suppressors." (PMID 29100300, 2017). "For example, some DUSPs exhibit loss of heterozygosity in some cancers with additional functional studies supporting potential roles as tumor suppressors, including DUSP4, DUSP6 and DUSP7." (PMID 25568665, 2014). "Although there are few reports linking DUSP7 to cancer, current evidence suggests that it may act predominantly as a tumour suppressor." (PMID 40943262, 2025). "The most abundantly studied are MAPK pathway inhibitors, and the common mechanisms of resistance are the reactivation of MAPK pathways such as DUSP7, NF2, and the KEAP1/Nrf2 pathway, which are present in multiple cancer resistance models." (PMID 38084101, 2023). "Another category of genes expressed during this time period are the dual specificity phosphatases, DUSP1, DUSP5, and DUSP7, which are involved in MAP/ERK signaling and can play roles in development or cancer." (PMID 23505351, 2013).
tumor (9 papers, 2014 to 2025). "The IHC results from the CC TMA analysis showed that the decreased expression of DUSP7 (p = 0.045 and 0.044) was significantly associated with a tumour size >2 cm and parametrial infiltration." (PMID 34435746, 2021). "Based on our data, the decreased expression of DUSP7 and increased expression of PLD1 were significantly associated with a tumour size >2 cm and parametrial infiltration." (PMID 34435746, 2021). "DUSP7 plays an important role not only in development, but also in tumours." (PMID 37962020, 2023). "However, the role of DUSP7 in the development of human tumours is still poorly understood and controversial." (PMID 34435746, 2021). "The IHC results from the CC TMA analysis showed that the decreased expression of DUSP7 (p = 0.045 and 0.044, respectively) and increased expression of PLD1 (p = 0.046 and 0.028, respectively) were significantly associated with a tumour size >2 cm and parametrial infiltration." (PMID 34435746, 2021). "In line with an antitumoural action of DUSP7, a recent work demonstrated that in CRC with SMAD4 deletion, SETD2, a histone methyltransferase, promotes the transcription of DUSP7, leading to inactivation of the RAS/ERK pathway and reduced tumour growth." (PMID 40943262, 2025).
infection (3 papers, 2010 to 2023). The state of being infected such as from the introduction of a foreign agent such as serum, vaccine, antigenic substance or organism. "Similar, in the chicken, DUSP1, DUSP5, DUSP7, DUSP10, DUSP15, and DUSP16 were significantly downregulated in response to infection." (PMID 36683094, 2023).
DUSP7 also shares sentences with these, for which no sentence is quoted: acute kidney injury (1 paper); acute myeloid leukemia (1); asthma (1); Astrocytoma (1); clear-cell renal cell carcinoma (1); colorectal cancer (1); epithelial ovarian cancer (1); infertile (1); leukemia (1); mesothelioma (1); pilocytic astrocytoma (1); psoriasis (1); renal carcinoma (1); renal cell carcinoma (1).